SUFU (SUFU negative regulator of hedgehog signaling)
Diseases named in the same sentence as SUFU in open-access papers (continued):
Sharing a sentence is not in itself a finding about the gene and the disease.
Joubert syndrome (6 papers, 2020 to 2025). Joubert syndrome (JS) is characterized by congenital malformation of the brainstem and agenesis or hypoplasia of the cerebellar vermis leading to an abnormal respiratory pattern, nystagmus, hypotonia, ataxia, and delay in achieving motor milestones. "WES data was initially filtered for biallelic changes in 38 genes known to cause Joubert syndrome and monoallelic changes in SUFU." (PMID 34423300, 2021). "Taken together, our data imply that the clinical phenotype associated with heterozygous truncating germline variants in SUFU is a forme fruste of Joubert syndrome." (PMID 33024317, 2021). "Aside from the common Joubert syndrome phenotypes such as hyperpnoea, eye movements and developmental retardation, calvarial bone formation has been linked to SUFU mutations." (PMID 32278351, 2020). "Comparing the clinical and neuroimaging features of the 15 subjects reported here with those known to occur in Joubert syndrome, we suggest addressing the clinical phenotype associated with heterozygous truncating germline variants in SUFU as a forme fruste of Joubert syndrome." (PMID 33024317, 2021). "More recently, additional 22 patients with SUFU haploinsufficiency and a neurodevelopmental phenotype at the mild end of the Joubert syndrome spectrum were reported." (PMID 37131188, 2023). "It was recently found that haploinsufficiency of SUFU (heterozygous LOF mutation) also presents with congenital ocular motor apraxia and neurodevelopmental delay with the mild Joubert syndrome phenotype." (PMID 34884862, 2021).
pancreatic cancer (6 papers, 2013 to 2023). "In pancreatic cancer, a germline mutation in SUFU was found associated with intraductal papillary mucosal neoplasms (IPMNs) and elevated risk of pancreatic carcinomas." (PMID 34298625, 2021). "We also included the down regulation or loss of function scenario of few proteins such as GAS1, SUFU, NUMB, SNO etc. in pancreatic cancer model." (PMID 23935937, 2013). "In agreement with the previous data in SUFU-deficient and pancreatic cancer cells, inhibition of DYRK1B but not of DYRK1A reduced GLI1 protein levels." (PMID 26784250, 2016). "On the other hand up regulation of SHH, STK36, ERK12, RAS and down regulation of SUFU were co-occurring in Pancreatic cancer cell line, hence in our second simulation (Simulation 2), we considered all these co-occurrence as initial states to provide biologically realistic predictions." (PMID 23935937, 2013). "The regulation of EMT by the Wnt signaling pathway has been determined including Wnt5a, FOXP3, SERPINH1, CUL4B, and SUFU, which can be used in BLCA, gastric cancer, and pancreatic cancer." (PMID 34579753, 2021). "Gedunin treated pancreatic cancer cells were effectively downregulated PTCH1, PTCH2, Gli1, SUFU and Shh proteins involved in Hedgehog/Gli signaling pathway." (PMID 26988754, 2017). "We found that umbelliprenin treatment did not change the protein expression level of β‐catenin, Shh, and SUFU, indicating that Wnt/β‐catenin and Hedgehog signaling pathways are not involved in the umbelliprenin‐mediated inhibition of pancreatic cancer cell stemness." (PMID 37409635, 2023).
breast carcinoma (5 papers, 2016 to 2023). "Notably, one family in the present study, with an accumulation of PDAC and breast cancer, revealed a pathogenic SUFU variant co-segregating with PDAC and a FANCM variant segregating with breast cancer." (PMID 34357098, 2021). "A co-segregating, potentially pathogenic SUFU germline variant was detected in another family, which must be considered as a PDAC/breast cancer family." (PMID 34357098, 2021). "For instance, DNM3OS downregulates Vitamin D receptor (VDR), and VDR is capable of upregulating Suppressor of fused gene (SuFu), while SuFu is an inhibitor of progression of breast cancer." (PMID 33745450, 2021). "Interestingly, Suppressor of fused homolog (SUFU) inhibits ferroptosis sensitivity in breast cancer cells through the Hippo/YAP pathway." (PMID 37521466, 2023). "In addition, we observed copy losses of the negative regulators SUFU, as well as of the tumor suppressor WWOX, a newly identified negative modulator of GLI1 in breast cancer." (PMID 27095580, 2016).
gastric cancer (5 papers, 2021 to 2024). A primary or metastatic malignant neoplasm involving the stomach. "Of importance, the epigenetic upregulation of both pathways was demonstrated to occur through miRNA-150-mediated downregulation of SUFU in gastric cancer, further supporting the crosstalk between the pathways." (PMID 38474826, 2024). "For example, Lan and colleagues discovered that M2M EV enhance colon cancer cell proliferation and invasion by delivery miRNA, and Yang and colleagues found that miR-423-5p promotes gastric cancer cell proliferation and metastasis through suppressing SUFU protein expressions." (PMID 38554157, 2024). "Additionally, it was demonstrated that MAPK pathway increased the transcriptional factors and regulated Gli1 through Hh/Suppressor of Fused (SUFU)-independent pathway in gastric cancer cell lines." (PMID 35834029, 2022).
ovarian carcinoma (5 papers, 2021 to 2025). A malignant neoplasm originating from the surface ovarian epithelium. "We analyzed the mRNA expression profiles of HH-related genes—SHH, HHAT, PTCH1, GLI1, GLI2, GLI3, and SUFU—in two ovarian cancer cell lines." (PMID 40565349, 2025). "Further investigation is required to discover the function of SUFU downregulation by SPOP in ovarian cancer." (PMID 34021128, 2021). "In addition to these genes, a high risk for ovarian cancer is associated with mutations in the DICER1, VHL, PTCH1, SUFU, SMARCB1, and SMARCA4 genes." (PMID 37685988, 2023). "Furthermore, ectopic expression of SPOP decreased SUFU protein levels in the kidney cancer cell line A498 and ovarian cancer cell line SKOV3, and siSPOP showed the opposite results, suggesting the physiological significance of this regulation in carcinogenesis." (PMID 34021128, 2021). "To assess their potential prognostic value, we analyzed the correlation between the expression levels of the following eight components of the Hedgehog signaling pathway on the progression-free (PFS) and overall survival (OS) in ovarian cancer: SHH, GLI1, GLI2, GLI3, PTCH1, PTCH2, HHAT, and SUFU." (PMID 40565349, 2025). "Using the database Kaplan–Meier plotter, which includes the gene expression and survival data of 1565 ovarian cancer patients, higher expression levels of the genes SHH, PTCH1, PTCH2, and GLI1 displayed better survival correlations, while GLI, GLI3, and SUFU correlated with adverse outcomes." (PMID 40565349, 2025). "In addition, we also observed a negative correlation between SPOP and SUFU accompanied by dysregulated SHH signaling in ovarian cancer." (PMID 34021128, 2021).
prostate carcinoma (5 papers, 2004 to 2022). A carcinoma that arises from epithelial cells of the prostate gland. "Hedgehog signalling has been implicated in prostate cancer development, metastasis and androgen-independent growth 44,45, so repression of SUFU by HES6 could represent a new mechanism whereby prostate cancer cells induce hedgehog signalling to promote aggressive behaviours." (PMID 25864518, 2015). "SUFU functions as a tumor suppressor in several malignancies, including lung cancer, prostate cancer, astrocytoma, glioblastoma, and GC." (PMID 33848981, 2021).
glioblastoma (4 papers, 2014 to 2025). The most malignant astrocytic tumor (WHO grade IV). "Nevertheless, somatic driver events in SUFU have been detected in the TCGA35 glioblastoma cohort (TCGA data), suggesting potential relevance in gliomagenesis, although the TCGA did not report recurrent SUFU homozygous deletions as a hallmark alteration." (PMID 41168197, 2025). "miR-378a-5p enhances cell survival, proliferation rate and angiogenesis in glioblastoma cells, through targeting of SUFU and TUSC2." (PMID 24651706, 2014).
melanoma (4 papers, 2013 to 2026). A malignant, usually aggressive tumor composed of atypical, neoplastic melanocytes. "Separated analysis of primary and metastatic samples revealed significantly lower expression of PTCH1 and SUFU in advanced melanoma, confirming the relevance of the Hh signaling pathway in melanoma progression." (PMID 41596411, 2026). "We observed reduced PTCH1 and SUFU repressors expression and GLI2 upregulation as common melanoma features." (PMID 41596411, 2026). "Gene expression profiling revealed downregulation of two repressors, PTCH1 and SUFU, along with upregulation of the downstream effector GLI2 in melanoma cells compared to normal melanocytes." (PMID 41596411, 2026). "Notably, cells derived from advanced metastatic lesions exhibited a more pronounced phenotype, characterized by significantly lower levels of three key repressor proteins, PTCH1, SUFU, and GLI3, compared to primary melanoma cells." (PMID 41596411, 2026). "The mRNA coding for GLI2, one of the most important downstream effectors of Hh signaling, was markedly upregulated (7.59-fold increase) in melanoma cells, whereas two key Hh repressors, PTCH1 and SUFU, were significantly reduced (0.341 and 0.458-fold decrease, respectively) compared to controls." (PMID 41596411, 2026). "Upregulation of miR-378a-5p in M14 melanoma cells reduced both mRNA and protein levels of STAMBP, SP1, KLF9, FUS-1, and SUFU when compared with control transfected cells, while miR-378a-5p inhibition led to an opposite effect, upregulating the expression of target genes." (PMID 32060259, 2020). "Effects of iRF on melanoma cells (B16F10 cells) are, at least in part, correlated with inhibition of HH signaling, as evident by the decreased the expression of key players in HH pathway signaling such as GLI1 and PTCH-1 and the increase of SUFU expression." (PMID 23342114, 2013).
lung carcinoma (3 papers, 2018 to 2021). "Further study to clarify whether SUFU is indeed involved in HH pathway activation or ER in lung cancer would be interesting." (PMID 30555633, 2018). "We next analyzed the expression levels of canonical SHH signaling components—such as PTCH1, PTCH2, SMO, SUFU, and GLI1 proteins—in cultured human lung cancer cells (H1299, A549, HCC827, and H1975) and normal human lung fibroblasts (MRC-9 and WI38) by western blot analysis." (PMID 31783569, 2019).
rhabdomyosarcoma (3 papers, 2012 to 2019). A rare aggressive malignant mesenchymal neoplasm arising from skeletal muscle. "In two cell lines from rhabdomyosarcoma, a tumor type associated with deregulated HH signaling, SUFU-ΔC mRNA was expressed at comparable levels as SUFU-FL mRNA, but at the protein level only low amounts of SUFU-ΔC were detectable." (PMID 22666390, 2012). "Genetic alterations, including mutations in PTCH, SUFU, and SMO lead to constitutive activation of the hedgehog pathway in BCC, rhabdomyosarcoma and MB." (PMID 31362788, 2019).
B-cell lymphoma (2 papers, 2024 to 2025). "In conclusion, our study uncovers a novel regulatory axis involving P4HA2, KIF7, and SUFU in the Hh signaling pathway, shedding light on the intricate mechanisms governing B-cell lymphoma tumorigenesis." (PMID 38909089, 2024). "Collectively, our observations suggest that P4HA2, along with the proline hydroxylation of SUFU, plays crucial roles in promoting B-cell lymphoma progression through a paracrine signaling transduction mechanism." (PMID 38909089, 2024). "SUFU can be hydroxylated by the complex of P4HA2 and KIF7, which inhibits its function and amplifies Hh signaling in B-cell lymphoma." (PMID 40170839, 2025).
bladder cancer (2 papers, 2021 to 2023). "To explore the association of ROC1, SUFU, and Gli2 expression with the tumor clinicopathological grade, we analyzed their expression immunohistochemically in human bladder cancer tissues." (PMID 33499884, 2021). "In addition, our current ex vivo data further revealed an association between ROC1 expression and the hedgehog pathway proteins, i.e., ROC1 expression was inversely associated with SUFU (P < 0.001) but positively associated with Gli2 expression (P < 0.001) in bladder cancer tissues." (PMID 33499884, 2021). "Collectively, bladder cancer tissues with low ROC1 expression had high SUFU and low Gli2 expression levels." (PMID 33499884, 2021). "To explore the molecules that are primarily responsible for hedgehog activation, we assessed SUFU expression in ROC1-knocked down or ROC1-overexpressed bladder cancer cells." (PMID 33499884, 2021). "We then divided their expression levels into two categories (low vs. high) and found that ROC1 and Gli2 expression was low, but SUFU expression was high in the low-grade bladder cancer tissues compared with those in high-grade tumors." (PMID 33499884, 2021).
colon cancer (2 papers, 2013 to 2024). "We also considered the down regulation or loss of function of few tumor suppressor proteins such as GAS1, SUFU, NUMB, SNO etc., while simulating the colon cancer scenario, which in normal situation inhibited the GLI proteins." (PMID 23935937, 2013).
mesothelioma (2 papers, 2021 to 2022). A usually malignant and aggressive neoplasm of the mesothelium which is often associated with exposure to asbestos. "Here, we describe alterations in Hedgehog signalling genes PTCH1 (1.2%) and SUFU (0.8%) in the whole mesothelioma cohort." (PMID 36138075, 2022). "SUFU inhibits activation of GLI transcription factors in the Hedgehog pathway, which is known to be disordered during mesothelioma carcinogenesis." (PMID 34580349, 2021). "Based on our data, targeted treatments might also become a possible approach for mesothelioma, as alterations in hedgehog pathway-related genes (e.g., PTCH1/2 and SUFU) and hippo pathway-related genes (particularly NF2) were found." (PMID 36138075, 2022).
neuroblastoma (2 papers, 2013 to 2023). Neuroblastoma (NB) is the most common solid, extracranial childhood tumor. "We also demonstrated that AKT2 overexpression regulates the nuclear-cytoplasmic distribution of exogenous Gli1 protein in neuroblastoma cells by relieving a GSK3β-mediated destabilization of SUFU, a negative regulator of Gli1 nuclear translocation." (PMID 23900341, 2013). "This confirms the negative role of SUFU in Gli1 transcriptional activity as previously demonstrated and a novel demonstration of the same in neuroblastoma." (PMID 23900341, 2013).
schizophrenia (2 papers, 2020 to 2023). A major psychotic disorder characterized by abnormalities in the perception or expression of reality. "We found that the schizophrenia risk variant rs10786700 regulates the expression of SUFU gene, which is highly expressed in the frontal cortex in early stage of development and in excitatory neurons." (PMID 36152315, 2023). "CRISPR-Cas9-mediated genome editing identified SUFU as a potential target gene by which rs10786700 might exert its risk effect on schizophrenia, as deletion of rs10786700 downregulated SUFU expression." (PMID 36152315, 2023). "Seven out of 18 genes are associated with neurological diseases: Alzheimer’s disease (CPT1A, SUFU, ZSWIM8, PDCD4), schizophrenia (HTT, NBEAL2) and Parkinson disease (PRDM13)." (PMID 32599769, 2020). "Interestingly, there were seven genes associated with neurological disorders, including Alzheimer’s disease (CPT1A, SUFU, ZSWIM8, PDCD4), schizophrenia (HTT, NBEAL2) and Parkinson’s disease (PRDM13)." (PMID 32599769, 2020).
schwannoma (2 papers, 2020 to 2025). A benign, usually encapsulated slow growing tumor composed of Schwann cells. "Particularly, ATM, accounting for 33% of the samples, was the most frequently mutated cancer-related gene in schwannoma, followed by CHD4, FAT1, KMT2D, MED12, NF2, and SUFU (>20%)." (PMID 33193598, 2020).
acute GVHD (1 paper, 2015). "In this study, a SNP in the SUFU gene (rs17114808) was found to be associated with the incidence of acute GVHD in two independent cohorts of pediatric and young adult patients who underwent allogeneic HSCT for a variety of underlying diagnoses and utilizing various transplant approaches." (PMID 26067905, 2015). "Thus our findings provide novel evidence that recipient SUFU germline polymorphism is associated with acute GVHD and is a novel molecular target for GVHD prevention and treatment." (PMID 26067905, 2015). "In summary, we identified SUFU as a novel molecular determinant for acute GVHD using genome-wide analysis." (PMID 26067905, 2015).
acute lymphoblastic leukemia (1 paper, 2022). Leukemia with an acute onset, characterized by the presence of lymphoblasts in the bone marrow and the peripheral blood.
Ataxia (1 paper, 2023). Ataxia refers to impaired coordination of voluntary muscle movement. "E. g., the “benign, idiopathic” variant with muscular hypotonia, mild developmental delay, and ataxia fits well with the forme fruste of JBTS associated with heterozygous truncating SUFU variants." (PMID 37131188, 2023).
Cerebellar dysplasia (1 paper, 2024). Cerebellar dysplasia (abnormal growth or development) is defined by abnormal cerebellar foliation, white matter arborization, and gray-white matter junction. "Loss of SHH pathway inhibition in neural stem cells and GCs from lack of GPR161 and SUFU, which promotes cleavage of GLI3 into the transcriptional repressor GLI3R, can lead to hyperproliferation and cerebellar dysplasia." (PMID 39137043, 2024).
childhood medulloblastoma (1 paper, 2019). A medulloblastoma occurring in children. "Some researchers question whether SUFU variant leads to GS or if it leads to a similar syndrome, with some of the same phenotypes but more centred around dermatological manifestations and childhood medulloblastoma." (PMID 31485359, 2019).
Coma (1 paper, 2021). The complete absence of wakefulness and consciousness, which is evident through a lack of response to any form of external stimuli. "Interestingly, we observed a higher basal activity of HH signaling in COMA patient–derived fibroblasts compared with control cells, supporting the hypothesis that the inhibitory function of SUFU is impaired by the identified SUFU variants." (PMID 33024317, 2021).
familial multiple meningioma (1 paper, 2021). Familial multiple meningioma is a rare, benign neoplasm of the central nervous system characterized by the development of multiple or, rarely, solitary meningiomas in two or more blood relatives, without other apparent syndromic manifestations. "SUFU (suppressor of fused homolog) protein acts downstream of SMO and loss of SUFU function has been implicated in familial multiple meningioma." (PMID 33262459, 2021).
folate deficiency (1 paper, 2023). A nutritional condition produced by a deficiency of FOLIC ACID in the diet. "Together, our results provide evidence that folate deficiency affects DOT1L activity and the levels of H3K79me2, which is related to abnormal expression of SHH, SUFU genes and subsequently NTDs." (PMID 38093377, 2023).
ganglioglioma (1 paper, 2018). A well differentiated, slow growing neuroepithelial neoplasm composed of neoplastic, mature ganglion cells and neoplastic glial cells. "We include the first report of a case with mixed features of both MVNT and conventional ganglioglioma in support of a potential common origin, and we identified two cases with novel mutations in SUFU and EZH2, although these mutations are of uncertain significance." (PMID 28833756, 2018).
head and neck carcinoma (1 paper, 2017). A carcinoma that arises from the head and neck region. "Few studies investigated the epigenetic regulation of Shh signaling in head and neck carcinomas; thus, we aimed to assess whether known negative regulators of this pathway (HHIP, PTCH1, SUFU, ZIC1, ZIC4) undergo methylation in HNSCC." (PMID 27553089, 2017).